LINC00392 (long independently transcribed non-coding RNA 392)
Gene: Long non-coding RNA gene on chromosome 13 (73,564,244 to 73,588,070, forward strand). Ensembl gene ENSG00000228295.
Diseases named in the same sentence as LINC00392 in open-access papers:
LINC00392 is named in the same sentence as 1 disease in open-access papers, as found by Europe PMC text mining. Sharing a sentence is not in itself a finding about the gene and the disease.
LINC00392 shares sentences with these, for which no sentence is quoted: tumor (1 paper).